LINC00513 (long independently transcribed non-coding RNA 513)
Synonyms: AC016831.7
Gene: Long non-coding RNA gene on chromosome 7 (130,794,561 to 130,939,666, forward strand). Ensembl gene ENSG00000233559.
Diseases named in the same sentence as LINC00513 in open-access papers:
LINC00513 is named in the same sentence as 2 diseases in open-access papers, as found by Europe PMC text mining. Sharing a sentence is not in itself a finding about the gene and the disease. The quoted sentences say what the papers report.
lupus (4 papers, 2018 to 2022). "Further, in SLE, the over expression of linc00513 plays a role in lupus pathogenesis by promoting IFN signalling pathway." (PMID 33668203, 2021). "Our data have showed the expression of linc00513 was elevated in lupus patients and linc00513 was a positive regulator of IFN pathway." (PMID 30619325, 2018). "In conclusion, our findings reveal the over expression of linc00513 plays a role in lupus pathogenesis by promoting IFN signaling pathway." (PMID 30619325, 2018). "Overexpression of linc00513 via promoting IFN signaling could play a role in lupus pathogenesis." (PMID 35572537, 2022). "Here in our study, we demonstrated rs205764 and rs547311 in the promoter of linc00513 could augment its transcription as determined by reporter gene assay and eQTL effect, thus making linc00513 a distinctly high expressed lncRNA in lupus patients and promoting disease development." (PMID 30619325, 2018). "Thus, we identified linc00513 as a novel robust regulator of type I IFN pathway, providing new evidence for the contribution of non-coding RNAs to the pathogenesis of lupus." (PMID 30619325, 2018).
LINC00513 also shares sentences with these, for which no sentence is quoted: tumor (1 paper).